HTN1 (histatin 1)
Description:
Histatins (Hsts) are cationic and histidine-rich secreted peptides mainly synthesized by saliva glands of humans and higher primates. Hsts are considered to be major precursors of the protective proteinaceous structure on tooth surfaces (enamel pellicle). Hsts can be divided into two major groups according to their biological functions: antimicrobial Hsts (e.g. Hst 5/HTN3) and cell-activating Hsts (e.g. Hst 1/HTN1 and Hst 2/HTN1). Hst 1/HTN1 and Hst 2/HTN1 act in different cell types (epithelium, fibroblasts and endothelium) in oral and non-oral mucosa. [Histatin-1]: Hst 1 functions primarily as a wound healing factor by activating cell-surface and cell-cell adhesions, cell spreading and migration and it can also stimulate cellular metabolic activity. Hst 1 is internalized in host cells in a stereospecific and energy-dependent process, which is partially mediated by the G protein-coupled receptors (GPCR)-activated endocytosis. Internalized Hst 1 is targeted and released via early endosomes trafficking to the mitochondria, where it significantly enhances mitochondrial energy metabolism. At the mitochondria, Hst 1 increases mitochondria-ER contacts through binding with ER receptor TMEM97, which also stimulates metabolic activity and cell migration and may as well regulate calcium homeostasis of the cell. Also activates the ERK1/2 signaling pathway to promote cell migration, possibly upon interaction with GPRCs at the plasma membrane. Also triggers the RIN2/Rab5/Rac1 signaling cascade which activates endothelial cell adhesion, spreading and migration required for angiogenesis in the oral wound healing process, however the receptor that transduces Hst 1 signal has not yet been identified. Also displays antimicrobial functions against pathogenic yeast Candida albicans, although with less effectiveness than Hst 5. [His1-(31-57)-peptide]: Hst 2 consists of the fragment sequence 12-28 of Hst 1. Similar to Hst 1, actively and stereospecifically internalized in host cells and targeted to the mitochondria and the ER and promotes cell metabolic activity. Also activates the ERK1/2 signaling pathway to promote cell migration and wound closure. In contrast with Hst 1, not able to promote cell-substrate and cell-cell adhesion.
Synonyms: Hst1; HIS1
Tractability: Antibody: its Gene Ontology location is reachable by antibodies, with high confidence; UniProt places it where antibodies can reach, with medium confidence; UniProt predicts a signal peptide or a membrane-spanning region.
Gene: Protein-coding gene on chromosome 4 (70,050,438 to 70,058,848, forward strand). Ensembl gene ENSG00000126550.
Subcellular location: Secreted (Histatin-1); Mitochondrion; Endoplasmic reticulum membrane; Secreted (His1-(31-57)-peptide)
Pathways (Reactome):
Immune System: Antimicrobial peptides
Gene Ontology:
Molecular function: protein binding
Biological process: positive regulation of cell-cell adhesion; positive regulation of metabolic process; positive regulation of substrate adhesion-dependent cell spreading; positive regulation of vascular wound healing; positive regulation of wound healing; positive regulation of wound healing, spreading of epidermal cells; antimicrobial humoral immune response mediated by antimicrobial peptide; defense response to bacterium; killing of cells of another organism
Cellular component: endoplasmic reticulum; endoplasmic reticulum membrane; mitochondrion; extracellular region
Homologues: Orthologues: chimpanzee HTN1 (96% identical). Paralogues in human: HTN3 (75% identical), STATH (39% identical).
Diseases named in the same sentence as HTN1 in open-access papers:
HTN1 is named in the same sentence as 12 diseases in open-access papers, as found by Europe PMC text mining. Sharing a sentence is not in itself a finding about the gene and the disease. The quoted sentences say what the papers report.
dental caries (4 papers, 2016 to 2025). The decay of a tooth, in which it becomes softened, discolored, and/or porous. "But on the other hand, this will provide much stronger evidence for histatin-1 as a candidate biomarker for dental caries." (PMID 27527350, 2016). "In our previous study, the STRING online database, we identified 63 interactions in saliva samples from children with and without dental caries, and reported associations among histatin-1, mucin-5B, mucin-7, and cystatin S." (PMID 30359274, 2018). "In the future, with the development of research technologies and improvement of peptidomic methodology, we are looking forward to performing more in-depth studies on the intrinsic mechanisms between histatin-1 and the occurrence and development of dental caries." (PMID 27527350, 2016). "On the other hand, 3 non-age-specific proteins, including histatin-1, BPI fold-containing family B member 1, and alpha-enolase were determined to be associated with dental caries." (PMID 30359274, 2018). "The results indicated strong correlations between high levels of phosphopeptides (PRP 1-3, histatin-1, and statherin) and the absence of dental caries." (PMID 27527350, 2016). "The expression levels of histatin-1 in populations across different age groups who are prone to dental caries are significantly lower than in those without caries, suggesting that histatin-1 may have important implications for the prevention and treatment of dental caries." (PMID 40007606, 2025). "Moreover, non-age-specific proteins (histatin-1 and BPI fold-containing family B member 1) were verified to be important candidate biomarkers for common dental caries." (PMID 30359274, 2018). "Moreover, two differentially expressed proteins, histatin-1 and BPI fold-containing family B member 1, were validated to be non-age-specific candidate biomarkers of dental caries, which may advance our utilization of salivary diagnostics for caries risk assessment." (PMID 30359274, 2018).
periodontitis (3 papers, 2022). An acute or chronic inflammatory process that affects the tissues that surround and support the teeth. "Recently, proteomic analysis of the saliva of Grade B Stage 2 periodontitis patients revealed that histatin-1, proline-rich phosphoprotein, thioredoxin, and cystatin-SA were increased in Grade B Stage 2 periodontitis." (PMID 35330371, 2022).
COVID-19 (1 paper, 2024). A disease caused by infection with severe acute respiratory syndrome coronavirus 2. "Bulk RNA-sequencing data from infected parotid glands tissue from deceased COVID-19 patients and uninfected control tissue demonstrated significantly reduced expression of histatin genes (HTN1, HTN3) (>100-fold)." (PMID 39666753, 2024).
fungal infection (1 paper, 2020). "The different patterns in hyphal colonization and DNA content confirm that the Htn1 gene does not offer a completely effective barrier against fungal infection." (PMID 33391321, 2020).
head and neck squamous cell carcinoma (1 paper, 2025). A squamous cell carcinoma that arises from any of the following anatomic sites: lip and oral cavity, nasal cavity, paranasal sinuses, pharynx, larynx, and salivary glands. "In addition, immunohistochemistry analysis of 98 samples of head and neck squamous cell carcinoma (HNSCC) showed higher expression of histatin-1, and a positive correlation between PD-L1 and histatin-1 was associated with the progression of HNSCC." (PMID 40507844, 2025).
Peri-Implantitis (1 paper, 2024). An inflammatory process with loss of supporting bone in the tissues surrounding functioning DENTAL IMPLANTS. "The effects of histatins in other epithelial tissues have been extended to the context of peri-implantitis, where histatin-1, embedded in a small intestine mucosa hydrogel, favored epithelial sealing around implant surfaces, thereby decreasing peri-implantitis." (PMID 39634559, 2024).
tumor (1 paper, 2024). "In the case of histatin 1 and histatin 3, we could identify only one peptide belonging to those proteins in one extract sample from tumor tissue; however, we suspect that such identification was caused by the imperfect separation of healthy tissue from tumor." (PMID 39201484, 2024). "no peptides derived from four saliva-specific proteins (SATH, SMR3B, HTN1, HTN3) were identified in extracts from tumor tissue." (PMID 39201484, 2024). "The lack of identification of peptides from proteins STATH, SMR3B, HTN1, and HTN3 in extracts from tumor tissues may suggest that there is a complete suppression of the production of these proteins in tumor tissues." (PMID 39201484, 2024). "The surprising result was that extracts from tumor tissue did not contain peptides derived from salivary gland-specific proteins (STATH, SMR3B, HTN1, HTN3)." (PMID 39201484, 2024). "However, regardless of the tumor type, the effect is the same: a lack of occurrence of peptides derived from proteins STATH, SMR3B, HTN1, and HTN3." (PMID 39201484, 2024). "Extracts derived from tumor tissue do not contain peptides derived from statherin (STATH) and three other proteins: submaxillary gland androgen-regulated protein 3b (SMR3B), histatin 1 (HTN1), and histatin 3 (HTN3)." (PMID 39201484, 2024).
HTN1 also shares sentences with these, for which no sentence is quoted: cancer (1 paper); head and neck cancer (1); infection (1); oral cancer (1); periodontal disease (1).